CD3E (CD3 epsilon subunit of T-cell receptor complex)
Diseases named in the same sentence as CD3E in open-access papers (continued):
Sharing a sentence is not in itself a finding about the gene and the disease.
asthma (3 papers, 2022 to 2025). "Additionally, different expressions of the Cd3e gene cause various human lung diseases, including asthma, and influence the severity and onset of symptoms." (PMID 40313552, 2025). "We observed that the mild, moderate, and severe asthma subject in the extreme low temperature group showed increased Tob1, Mub2, Sic34a2, Sftpc, Nxnl, Luc71, Lamp3, Gpr171, Cox14, and Cd3e expression, while in the severe asthma subjects showed increased expression in all temperature exposure group." (PMID 40313552, 2025). "CD3e has also been shown to be involved in the development of asthma." (PMID 35184642, 2022). "Additionally, subjects with severe asthma were more sensitive to low, high temperature and temperature fluctuation conditions, with increased of Tob1, Mub2, Sic34a2, Sftpc, Nxnl, Luc71, Lamp3, Gpr171, Cox14, and Cd3e expression." (PMID 40313552, 2025). "There was a significant positive correlation between IL15 expression and markers of T cells, including CD3E and CD8A but did not include CD4, suggesting the presence of nested CD8+ T cells in the airways of patients with asthma as previously observed." (PMID 40048261, 2025).
atherosclerosis (3 papers, 2011 to 2022). A disease characterized by the build-up of fatty material and calcium deposition in the arterial wall resulting in partial or complete occlusion of the arterial lumen. "Also, the total macrophages (CD68+), M1 pro-inflammatory macrophages (MHC-II+), and the immune cell infiltrate represented by T lymphocytes (CD3e+) that support the inflammatory process characteristic of atherosclerosis were followed." (PMID 35478972, 2022). "To explore whether rSj-Cys reduces the development of atherosclerosis by stimulating Treg, we detected the Treg-expressed CD3ε, CD4, and CD25 on the surface and the intracellular expression of Foxp3 in splenocytes." (PMID 34901005, 2021). "In contrast, the individuals with atherosclerosis in our study demonstrated a reduction in the expression of genes which contribute to T cell activation and maturation (CD3, CD3E, CD6, CD27)." (PMID 21698167, 2011).
autoimmune disease (3 papers, 2019 to 2024). A disorder resulting from loss of function or tissue destruction of an organ or multiple organs, arising from humoral or cellular immune responses of the individual to their own tissue constituents. "CD3E monoclonal antibodies have been utilized to modify the immune response, lower T-cell responsiveness to self-antigen, and treat autoimmune disorders." (PMID 35237542, 2022). "We designed a custom T cell panel to detect CD3ε, CD4, CD8α and FoxP3 in murine tissue to characterize T cell infiltrates in murine syngeneic tumors and autoimmune disease models." (PMID 38605049, 2024).
combined immunodeficiency (3 papers, 2020 to 2025). A broad classification of inherited disorders presenting at birth that affect both the cell-mediated and humoral aspects of the immune response. "CD3E usually participates in encoding the CD3ε chain, one of the major components (γ-, δ-, ε- and ζ-chain) of the CD3 co-receptor complex, whose deficiency will cause the severe combined immunodeficiency." (PMID 33748188, 2021).
gastric cancer (3 papers, 2020 to 2022). A primary or metastatic malignant neoplasm involving the stomach. "As for the CD3ε MFI value, we detected just a minor, not significant, reduction in the level of the CD3ε chain on the cell surface in gastric cancer compared to healthy subjects." (PMID 33354577, 2020). "TCRζ and CD3ε expression was also analyzed in tissue-derived (tumoral or nontumoral) T lymphocytes from patients with gastric cancer (n = 5) and control individuals (n = 5) subjected to surgery for reasons other than cancer." (PMID 33354577, 2020).
glomerulonephritis (3 papers, 2015 to 2025). A renal disorder characterized by damage in the glomeruli. "Glomerulonephritis samples additionally showed expression of collagen (COL1A1) and immune cell markers for monocytes or macrophages (LYZ and CD163) and T cells (CD3D, CD3E and CD3G)." (PMID 41028563, 2025). "Real-time PCR analysis of whole kidneys identified a marked increase in the gene expression of leukocyte markers (CD68, CD3e), proinflammatory cytokines (TNF-α, IFN-γ, CCL2) and macrophage elastase (MMP-12) in untreated and vehicle-treated mice at day 15 of glomerulonephritis." (PMID 26700873, 2015).
hepatocellular carcinoma (3 papers, 2022 to 2025). A malignant tumor that arises from hepatocytes. "Key markers, such as PTPRC, CD3E, CD4, CD79A, and CD3G in immune cells, EPCAM and KRT19 in epithelial cells, and MME and PECAM1 in stromal cells, were identified, providing crucial insights into hepatocellular carcinoma progression and immune response mechanisms." (PMID 39388011, 2024).
influenza (3 papers, 2014 to 2023). An acute viral infection of the respiratory tract, occurring in isolated cases, in epidemics, or in pandemics; it is caused by serologically different strains of viruses (influenzaviruses) designated A, B, and C, has a 3-day incubation period, and usually lasts for 3 to 10 days. "In addition, the virosome influenza vaccine induced significant proliferation of CD3e+CD8α+IFNγ+ T cells in swine, similar to previous studies in vaccinated mice, and pigs inoculated with a nanoparticle-adjuvanted influenza vaccine." (PMID 37587490, 2023).
lung diseases (3 papers, 2015 to 2025). "In conclusion, CD3ε−/− mice showed clear evidences of both liver and lung diseases 3 weeks post MCMV infection, in agreement with the high viral loads found at that time in these organs." (PMID 25747674, 2015). "TCF7 interacts with multiple proteins and target genes (e.g. CD3E, β-catenin, TCF7L2, LEF-1, IL-17, IL-4, or Eomes) and is involved in several signal pathways (e.g. Wnt, FoxO1, Notch, or P21pathways) which are critical for lung diseases, especially the canonical Wnt/β-catenin pathway." (PMID 26289446, 2015).
myeloma (3 papers, 2020 to 2024). "Following the optimization of various pairs of two subunits of TCR/CD3 complex, B-3G-C-3E TRuC-T cells, characterized by incorporating CD3γ and CD3ε, exhibited the strongest myeloma-specific cytotoxicity." (PMID 39776916, 2024). "BiTE, a special BsAb, can physically bind BCMA and CD3ε on T-cell receptors (TCR) for redirecting T cells to myeloma cells to exert its cytotoxicity." (PMID 35320942, 2022).
Obesity (3 papers, 2014 to 2025). Accumulation of substantial excess body fat. "Here, we observed the Th2 cells-transferred CD3ε−/− mice exhibited reduced fat accumulation accompanied by improvement of insulin sensitivity and glucose tolerance compared with CD3ε−/− counterparts, indicating that Th2 cells limit the pathogenesis and progression of obesity." (PMID 38195424, 2024).
pancreatic cancer (3 papers, 2022 to 2025). "Moreover, LGALS4 was shown to induce apoptosis in T cells by binding CD3ε/δ and driving immune evasion in pancreatic cancer." (PMID 39857769, 2025). "Several proteins with known roles in tumorigenesis such as FN1, TSPO, CD3E, and ZAP70 were present in the modules, which may be explored further as novel drug targets in pancreatic cancer." (PMID 36923555, 2022).
primary immunodeficiency (3 papers, 2016 to 2025). "Primary immunodeficiency was specifically inhibited (p = 0.0041), reflecting the up regulation of Cd8 (marker for cytotoxic T cells), Cd3δ, Cd3ε (required for differentiation of pro-T cells into pre-T cells) and Lck (required for Cd4+Cd8+ T cell differentiation into Cd8+ T cells)." (PMID 27515027, 2016). "GSEA analysis adds more insight into the 23 ERBB2-related DEGs and primary immunodeficiency signaling pathway, showing that ERBB2-related DEGs associated with primary immunodeficiency were mainly down-regulated ERBB2-related DEGs, such as CD79A, CD19, CD3D, CD3E, CD8A, and CD4." (PMID 36437939, 2022). "The circle plot representation of KEGG results highlighted specific enrichments: CD3E and CD8A were significantly enriched in primary immunodeficiency, while GZMB and PRF1 were notably enriched in allograft rejection." (PMID 39974584, 2025).
sarcoma (3 papers, 2018 to 2020). A usually aggressive malignant neoplasm of the soft tissue or bone. "Analysis of the TCGA confirmed significant differences in survival among human sarcoma patients with high and low expression of genes associated with greater immune activation and cytotoxicity (CD3e, CD8a, IFN-γ, perforin, and CD122/IL-2 receptor beta)." (PMID 32084139, 2020). "The correlations between the expression of IFN-γ and CD3E, CD8A, and CD45RO were then validated by analysis using GSE2719 or GSE967 datasets of sarcoma." (PMID 29896199, 2018). "Correlation analyses using sarcoma data of TCGA showed that the expression of IFN-γ was positively correlated with that of CD4 and CD45RO, but strong positive correlations were observed with CD3E and CD8A expression." (PMID 29896199, 2018).
seminoma (3 papers, 2023 to 2025). A radiosensitive malignant germ cell tumor found in the testis (especially undescended), and extragonadal sites (anterior mediastinum and pineal gland). "In line with the high inter-patient variation observed in our study, differential expression of CD3D, CD3E, and genes associated with TIL senescence were reported in two seminoma subtypes by other groups." (PMID 38649788, 2024). "To further examine the functions of MMP9 and CTSK in seminoma, we subset immune cells (PTPRC+), and explored the expression patterns of markers for T cells (CD3D+ and CD3E+) and B cells (CD79B+; MS4A1+ and SDC1+)." (PMID 38123589, 2023).
astrocytoma (2 papers, 2010 to 2021). "Significantly elevated CD3E expression was found in astrocytoma samples (n = 194) compared with oligoastrocytoma samples (n = 130, P = 6.43 × 10-4) or oligodendroglioma samples (n = 130, P = 6.4187 × 10-4)." (PMID 34557404, 2021). "Additionally, the CD3ε mRNA level in astrocytoma is 941±323% and increases in oligodendroglioma and GBM (7515% and 5231±1942%)." (PMID 21060663, 2010).
autoimmune disorders (2 papers, 2022). "The increased expression of CD5 on T cells and B cells can prevent autoimmunity, and CD3E is positively associated with some T cells and macrophages." (PMID 36118358, 2022).
chronic granulomatous disease (2 papers, 2023 to 2025). Chronic granulomatous disease (CGD) is a rare primary immunodeficiency, mainly affecting phagocytes, which is characterized by an increased susceptibility to severe and recurrent bacterial and fungal infections, along with the development of granulomas. "Finally, we and others observed suppressed murine Treg expansion in Ncf1*/* mutant chronic granulomatous disease (CGD) mice with anti-CD3ε/CD28 stimulation, which was reestablished during Treg polarization with robust TGFβ signaling." (PMID 41300507, 2025).
Hepatic fibrosis (2 papers, 2020 to 2023). The presence of excessive fibrous connective tissue in the liver. "Therefore, our findings revealed that T cell deficiency in CD3e knockout mice causes worm-load increase but inhibited liver fibrosis." (PMID 33347431, 2020). "Importantly, Cd3e−/− SD rats also exhibited identical phenotype of liver granuloma and hepatic fibrosis as observed in the Lck−/− SD rats when the infected liver sections were analyzed by H&E staining and Masson’s trichrome staining, as well as by qPCR analyses of fibrosis related marker genes." (PMID 33347431, 2020). "Consistent with previous studies that absence of T cells attenuated liver granuloma and hepatic fibrosis, CD3e−/− B6 mice selectively deficient in T cells had dramatic decrease of myeloid cell accumulation and significantly mitigated liver granuloma and fibrosis following schistosome infection." (PMID 33347431, 2020).
lymphopenia (2 papers, 2018 to 2021). Reduction in the number of lymphocytes. "Unlike the slow rate of lymphopenia-induced homeostatic proliferation (LIP), the rapid and robust form of proliferative responses has been documented for naïve T cells particularly in a chronic lymphopenic host such as RAG−/− and TCRβ−/− (and also CD3ε−/−) mice." (PMID 30190718, 2018).
malignant glioma (2 papers, 2020 to 2023). A grade III or grade IV glioma arising from the central nervous system. "hEGFRvIII:CD3 bi-scFv is comprized of two single chain antibody fragments (bi-scFvs) that bind mutant epidermal growth factor receptor variant III (EGFRvIII), a mutation frequently seen in malignant glioma, and human CD3ε on T cells, respectively." (PMID 32273346, 2020).
metastatic melanoma (2 papers, 2019 to 2021). A melanoma that has spread from its primary site to another anatomic site. "To examine how the relationship between CD3E expression and PDCD1 expression influences response to anti-PD-1 therapy, we analyzed RNA-Seq transcriptome data from pretreatment samples of 26 metastatic melanoma patients who received anti-PD-1 therapy." (PMID 31360302, 2019). "When examining anti-PD-1 responders and nonresponders in metastatic melanoma, scholars found a significantly higher correlation between CD3E and PD-1 between responders and nonresponders, which supports the tumor hypothesis related to CD3E expression in the microenvironment." (PMID 34124265, 2021).
myeloid leukemia (2 papers, 2021 to 2022). A clonal proliferation of myeloid cells and their precursors in the bone marrow, peripheral blood, and spleen. "In agreement with this assumption, MLL-AF4 sPTRS induced myeloid leukemia in the B220− CD3e− CD11b+ immunophenotype." (PMID 36335100, 2022).
prostate carcinoma (2 papers, 2022). A carcinoma that arises from epithelial cells of the prostate gland. "Other drugs classified as IO included an adenosine receptor antagonist, an indoleamine‐pyrrole 2,3‐dioxygenase inhibitor, two oncolytic viruses and a bispecific antibody targeting CD3ε on T‐cells and prostate‐specific membrane antigen in refractory prostate cancer." (PMID 34245134, 2022). "In this study, we performed next-generation sequencing-based gene expression analysis in peripheral blood from prostate cancer patients obtained pre- and post-radiotherapy and found six independently down-regulated genes including CCR7, FCGR2B, BTLA, CD6, CD3D, and CD3E." (PMID 36291815, 2022). "In this study, we performed gene expression analysis on peripheral blood from prostate cancer patients obtained post- radiotherapy and showed that 6 genes, including CCR7, FCGR2B, BTLA, CD6, CD3D, and CD3E, were down-regulated by a range of 1.5–2.5-fold as compared to pre-radiotherapy samples." (PMID 36291815, 2022).
thymoma (2 papers, 2021 to 2024). A neoplasm arising from the epithelial cells of the thymus. "In these assays, a T-cell stimulator (TCS) cell, which is a murine thymoma-derived cell line (BW5417) engineered to express a membrane-bound single-chain Fv (scFv) variant of the anti-CD3ε antibody OKT3, is used as the APC." (PMID 38073578, 2024). "Interestingly, LCK and CD3E had a generally positive correlation with those eight immune checkpoint genes for pan-cancers, except for thymoma." (PMID 35004669, 2021).
Type 1 diabetes (2 papers, 2021 to 2024). "Teplizumab (DB06606) targets CD3E being investigated for treating Type 1 diabetes (T1D)." (PMID 38166628, 2024).
uveitis (2 papers, 2017 to 2025). An inflammatory process affecting a part of or the entire uvea. "In this study, we showed that treatment with a novel rat IgG2a anti-mouse CD3ε Ab, Dow2, significantly reduced ocular inflammation in EAU models of noninfectious human uveitis." (PMID 28743289, 2017).
(HCMV) infection (1 paper, 2025). "The adaptive-like NK cells featured high expression of CD3E, LAG3, and IL-32 with no expression of FCER1G and TCRs, consistent with published scRNA-seq data (except for low expression of KLRC2/NKG2C, the canonical markers for adaptive NK cells after human cytomegalovirus (HCMV) infection) 21,22." (PMID 40394087, 2025).
/T-cell neoplasm (1 paper, 2018). "Extranodal NK/T-cell lymphoma (ENKTCL) is a highly aggressive mature NK/T-cell neoplasm marked by NK-cell phenotypic expression of CD3ε and CD56." (PMID 29761078, 2018).
brain tumors (1 paper, 2021). "Therefore, we hypothesized that CD3E may promote the immune evasion mechanism of brain tumors by causing T cell dysfunction in the immune cell population." (PMID 34557404, 2021). "In the previous bioinformatics analysis, we found through single cell analysis of brain tumors that the expression of CD3E is particularly prominent in CD8+ T cells." (PMID 34557404, 2021). "The role of CD3E in brain tumors is completely different from that of extracranial tumors." (PMID 34557404, 2021). "Therefore, we hypothesize that CD3E possibly contributes to an immune evasion mechanism in brain tumors by leading to T cell dysfunction." (PMID 34557404, 2021).
breast adenocarcinoma (1 paper, 2022). "We also use 88 duplicate images of the 64-channel CODEX Human FFPE breast adenocarcinoma and test Mistic on seven channels: Keratin14, FoxP3, CD34, CD8, CD3e, CD68, and perlecan." (PMID 35845830, 2022).
Burkitt lymphoma (1 paper, 2023). A rare form of malignant mature B-cell non-Hodgkin lymphoma. "Next, NSG mice were s.c. inoculated with the Raji cell line, a CD19+ Burkitt lymphoma cell line, to evaluate the anti‐tumor activity of CD19/CD3ε FP T cells and CD19 CAR‐T cells." (PMID 38023726, 2023).
Candidemia (1 paper, 2025). A form of invasive candidiasis where species of CANDIDA are present in the blood. "To evaluate therapeutic potential, we used humanized CD3ε transgenic mice with systemic candidemia." (PMID 40953078, 2025).
cardiac hypertrophy (1 paper, 2021). "Histological analysis confirmed the cardiac hypertrophy is caused by cardiomyocyte enlargement in CD3ε-/- mice." (PMID 34745139, 2021).
cerebral malaria (1 paper, 2019). A sequestration of Plasmodium falciparum in the brain, which can cause coma and/or seizures. "Recently, it has been reported that TCRαβ-expressing macrophages accumulate in the brain during experimental cerebral malaria, but in contrast to our data, those macrophages are mainly TCRαβ+, not CD3ε cells." (PMID 31787969, 2019).
Chronic colitis (1 paper, 2016). A chronic inflammatory disease of the large intestine (colon, cecum and rectum). "Studies have shown that improvements following LcS treatment on DSS-induced chronic colitis were associated with a decrease in IFN-γ production and an increase in IL-4 production in LI-LPMC, when stimulated with CD3ε/CD28." (PMID 27500935, 2016).
Cm (1 paper, 2015). "We found lung Cm infection did induced IL-9 production by CD45+ and more specifically CD4+ T cells (CD4+CD3ε+)." (PMID 25646821, 2015).
colorectal tumors (1 paper, 2021). "As splenic PD-1 expression highly correlated with splenic CD3e expression, we subdivided PD-1 protein expression levels into mice harboring colorectal tumors with a score of 0–3 or 4–5." (PMID 34830971, 2021).
dermatitis (1 paper, 2024). An inflammatory process affecting the skin. "When Dsg3H1-pTh17 cells were transferred into irradiated syngeneic wild-type C57BL/6 mice, they induced dermatitis at a slower rate than in Cd3e KO recipients (which lack endogenous T cells and showed EAD with kinetics similar to Rag2 KO recipients)." (PMID 38226171, 2024).
dysplasia (1 paper, 2024). A usually neoplastic transformation of the cell, associated with altered architectural tissue patterns. "Our analysis demonstrated that CD3-ε expression within the stroma was decreased compared with normal squamous epithelium across all stages of dysplasia and cancer." (PMID 38781019, 2024).